TSLP (thymic stromal lymphopoietin)
Diseases named in the same sentence as TSLP in open-access papers (continued):
Sharing a sentence is not in itself a finding about the gene and the disease.
infection (105 papers, 2008 to 2025). The state of being infected such as from the introduction of a foreign agent such as serum, vaccine, antigenic substance or organism. "Alarmins are epithelial-derived cytokines, such as thymic stromal lymphopoietin (TSLP), interleukin 33 (IL-33), and IL-25, released in response to the cellular damage caused by cellular stress or infection." (PMID 38201921, 2023). "The cytokines interleukin 33 (IL-33), thymic stromal lymphopoietin (TSLP) and IL-25 act as alarmins released due to cell damage caused by infection or other cellular stress." (PMID 36483186, 2022). "In contrast, mice rectally immunized with M2e in the presence of IFN-λ or TSLP showed less severe weight loss and most of these animals survived the challenge infection." (PMID 34659250, 2021). "In contrast, weight loss of mice immunized with the TSLP-supplemented HA vaccine was minimal and all animals survived the challenge infection." (PMID 34659250, 2021). "Interesting, the expression of TSLP mRNA was more highly evident and associated with bronchial epithelial cell area in male mice at 4-weeks post-infection, whereas IL-33 appeared to be more contained and associated with alveolar areas as assessed by RNAscope." (PMID 31076663, 2019). "Here, we show that TSLP levels are increased in the serum after infection of mice with T. congolense and deficiency of TSLP signaling as seen in TSLPR−/− mice results in susceptibility during the chronic phase of T. congolense infection in mice." (PMID 28769924, 2017). "Mice model studies showed that a cytokine, thymic stromal lymphopoietin (TSLP), causes a delay in Th1-like immune response, ultimately stimulating cytokines related to a Th2-like profile with increased neutrophil infiltration upon infection." (PMID 41471232, 2025). "The decrease of eosinophil levels in PEC was associated with higher levels of CCL11, TSLP, and IL-5 in the peritoneum, suggesting that infected animals increase the levels of these cytokines and chemokine to promote eosinophil differentiation during infection." (PMID 33042162, 2020). "Additionally, infection of mice with 2 recent clinical isolates of RSV with known human pathogenic potential similarly induced IL-13–producing ILC2s through a TSLP-dependent mechanism." (PMID 27156176, 2016). "Intranasal immunization with the SARS-CoV-2 subunit vaccine supplemented with TSLP can effectively protect mice against infection by SARS-CoV-2 wild-type and Delta B.1.617.2 strains." (PMID 40035515, 2025). "Thymic stromal lymphopoietin (TSLP) works synergistically with Th2 cytokines to regulate infection, inflammation, and metabolic homeostasis." (PMID 41294800, 2025). "Upon exposure to external insults such as injury and infection, the epithelium releases alarmins including interleukin-25 (IL-25), IL-33, and thymic stromal lymphopoietin (TSLP), which assist in initiating and amplifying the immune response." (PMID 41246133, 2025). "Various other studies have replicated a necessity for TSLP signalling in the expulsion of HD Tm infection, but how it contributes to type two immunity precisely remains poorly characterised." (PMID 40944312, 2025). "Factors influencing epidermal destruction such as damage or infection stimulate keratinocytes to produce pro-inflammatory cytokines like IL-25, IL-33, and thymic stromal lymphopoietin (TSLP), which activate Th2-mediated immune responses." (PMID 39728140, 2024). "Alarmin cytokines, such as IL-25, IL-33, and TSLP, are secreted by various immune and epithelial cells in response to tissue damage, infection, or inflammation." (PMID 38396704, 2024). "Here, we show that thymic stromal lymphopoietin (TSLP) and IL-5+ type 2 innate lymphoid cells are also required to maintain dermis-resident macrophages and promote infection." (PMID 38030609, 2023). "Both TSLP signaling and IL-5+ innate lymphoid cell 2 (ILC2s) were shown to maintain the number of dermal TRMs and promote infection." (PMID 37066418, 2023).
infection (continued). "IL-33, similar to IL-25 and thymic stromal lymphopoietin (TSLP), is an alarmin secreted from epithelial barrier cells when damaged by external stimuli from exposure to trauma, infection, or allergen." (PMID 37296626, 2023). "Infection with NTHi is also associated with transcriptional upregulation of cytokines CCL2 (MCP1), TNF, IL-1β, IL-6, CXCL8 and alarmins (TSLP, IL-33 and IL-25)." (PMID 37180449, 2023). "TSLP, interleukin (IL)-25, and IL-33 are three alarmin-type cytokines that are initially generated by epithelial cells in response to infection by RNA viruses including coronaviruses." (PMID 36851770, 2023). "A significant increase in TSLP immunofluorescence was observed upon infection by SARS-CoV-2 in NHBEs, suggesting the de novo synthesis of this cytokine in response to the virus." (PMID 36851770, 2023). "As CCL24 was produced by the dermal TRMs themselves, the current studies unveil an additional layer of TRM self-maintenance involving their production of TSLP, which was required to maintain the number of IL-5+ ILC2s in the site of infection." (PMID 38030609, 2023). "Recently, TSLP was reported to limit the memory CD8+ T‐cell recall response against secondary infection with influenza virus." (PMID 37165746, 2023). "Keratinocytes respond to skin damage and/or infection by producing “alarmin” cytokines: IL-25 (IL-17E), IL-33, and thymic stromal lymphopoietin (TSLP)." (PMID 36830738, 2023). "According to a recent study, enterocytes infected with HEV strongly increase the secretion of thymic stromal lymphopoietin, which induces inflammation and tissue injury during infection." (PMID 35891218, 2022). "A distinct subset of 8 cytokines (e.g. TSLP) and 140 metabolites (e.g. quinolinate) in sera identified those with a fatal outcome to infection." (PMID 35574937, 2022). "Measuring the release of 54 inflammatory mediators confirmed the transcriptomic data and revealed sustained production of tolerogenic factors (IL-27, IL-10, IL-1RA, TSLP) despite infection." (PMID 34367171, 2021). "In contrast, IL-25 and TSLP levels fluctuated over the course of infection, peaking around the tenth week of infection, with TSLP at much lower levels than IL-25." (PMID 33482904, 2021). "RV-C15 infection induced airway expression of IL-25, IL-33 and TSLP, innate cytokines responsible for activation of IL-5- and IL-13-producing ILC2s expansion." (PMID 33968043, 2021). "In one study, anti-IL-33 treatment and TSLP receptor deficiency blocked the infection-induced expression of IL-25 in lung epithelial cells, and ex vivo treatment of ILC2 with TSLP increased their expression of IL-25 and IL-33 receptors." (PMID 33482904, 2021). "We next assessed the effects of TSLP signaling on CD8+ T-cell recall responses at day 8 after secondary infection by RNA-Seq." (PMID 33439121, 2021). "Innate cytokines, including TSLP, IL-25 and IL-33, which are secreted following infection of murine and human airway epithelial cells by RSV, are known inducers of ILC2 differentiation and activation." (PMID 32375305, 2020). "TSLP is a cytokine found to be elevated during asthma, contributing to the pathogenesis of the infection, and promoting a TH2 cytokine response through DCs." (PMID 32545470, 2020). "At 4 weeks post-infection, male mice had higher levels of TSLP and IL-33 in the lungs, as well as increased airway mucus visualized by PAS staining and by levels of Muc5ac by quantitative PCR, more lung ILC2, DCs, and OX40L+ cells compared to female mice." (PMID 32397226, 2020). "Similar reductions in AHR and levels of IL-5 and IL-13 in the BALF were seen after re-infection when anti-TSLP was administered prior to the primary infection of neonatal mice compared to mice administered a control antibody." (PMID 32397226, 2020).
infection (continued). "Regarding the hMPV infection of AECs, it seems to induce a TH2 response against infection due to the secretion of TSLP and IL-33." (PMID 32545470, 2020). "Initial RSV response is driven by innate cytokines, such as IL-25, IL-33, and thymic stromal lymphopoietin (TSLP) that are released from the airway epithelial cells following infection." (PMID 32375305, 2020). "For instance, in the mouse model of RSV infection, anti-TSLP antibodies administered either 6 or 36 hours after infection resulted in a significant decrease in IL-13-expressing ILC2." (PMID 32397226, 2020). "This phenomenon was also seen in NHBEs cells obtained from asthmatic patients and infected with hRSV, as TSLP concentration were high when compared to healthy patients with hRSV-infection." (PMID 30936869, 2019). "A previous report showed that IKKβΔIEC mice are unable to produce TSLP and mount the mucosal Th2 responses required to eradicate infection with the gut-dwelling parasite Trichuris." (PMID 30123215, 2018). "In rat primary airway epithelial cell cultures, infection with RSV triggers an immediate increase in TSLP mRNA and protein, which induces myeloid DCs to express markers associated with Th2 polarization." (PMID 29915592, 2018). "At a later time of infection (16 h), reduced expression of IL-23α, TSLP, hBD2 and S100A7 was observed following keratinocyte infection with T3SS mutant strain compared to wild-type strain." (PMID 30070169, 2018). "LEPCs release innate cytokines, such as TSLP, IL-33, and IL-25, in response to infection or various environmental factors." (PMID 30056803, 2018). "We found increased level of TSLP in the serum of mice infected with T. congolense suggesting a possible role of this cytokine during infection." (PMID 28769924, 2017). "We observed an increased TSLP level in mice after infection with T. congolense, suggesting a role for this cytokine in resistance to the infection." (PMID 28769924, 2017). "We identified a significant increase in the total concentration of TSLP in the lungs of RSV-infected mice compared with mock-infected mice at 12 hours after infection." (PMID 27156176, 2016). "One potential explanation for these data is the continued production of TSLP in the lungs beyond 12 hours after infection, which is physiologically significant but less than the limit of detection of the ELISA." (PMID 27156176, 2016). "Concomitantly with elevated levels of Th1 indicators (IL-12, IFN-γ and iNOS), primary infections induced increased expression of several Th2 markers (IL-33, TSLP, ArgI and Ym-I) and other cytokines such as IL-9." (PMID 27658962, 2016). "A protective role of TSLP in intestinal immunity to T. muris has been well described; mice which are knockouts for IKKβ fail to produce TSLP in response to infection, and subsequently develop chronic intestinal inflammation." (PMID 25101088, 2014). "In either case, TSLP may contribute to B cell responses to HD Tm as a means of modulating immunity, but whether TSLP production during infection in fact occurs in the lymph node, where B cells would mediate their role, is not clear." (PMID 40944312, 2025). "Furthermore, histological analysis of the lung pathological damage revealed that compared with mice immunized with the S1 vaccine alone, lung damage in mice immunized with S1 supplemented with TSLP was reduced after SARS-CoV-2 WT or Delta strain infection." (PMID 40035515, 2025). "Additionally, upon damage or infection, airway epithelial cells secrete alarmins, such as the cytokines thymic stromal lymphopoietin (TSLP), IL‐25, and IL‐33." (PMID 41310922, 2025). "Our research indicates that TSLP can effectively boost SARS-CoV-2 subunit vaccine-specific systemic and mucosal humoral immunity in mice after intranasal immunization, protecting them from SARS-CoV-2 wild-type and Delta variant infection." (PMID 40035515, 2025).
infection (continued). "TSLP release in response to RV infection and stimulation with IL-4 was significantly increased in asthmatic BECs as compared with healthy BECs, and the same was observed after stimulation with IL-4 and IL-13 on top of infection with RV." (PMID 40370530, 2025). "Mechanical injury, infection, inflammatory cytokines and proteases such as trypsin and papain stimulate the release of various cytokines of epithelial origin, such as thymic stromal lymphopoietin (TSLP), interleukin-25 (IL-25), interleukin-33 (IL-33) and periostin." (PMID 40981017, 2025). "Interestingly, the intestinal adiponectin expression was strongly associated with the expression of epithelial cell-derived cytokines IL-25, IL-33, and TSLP following infection." (PMID 37635188, 2023). "Additionally, we determined if other epithelial cell types that are SARS-CoV-2-compliant express TSLP in response to infection." (PMID 36851770, 2023). "Furthermore, cells that expressed SP immunofluorescence (SP+) indicating infection by SARS-CoV-2 virus showed a significant increase in intracellular TSLP compared to mock-infected and SP- SARS-CoV-2-infected cells (p < 0.0001, p = 0.005, respectively)." (PMID 36851770, 2023). "Selective ablation of TSLP in dermis-resident macrophages reduces the numbers of IL-5+ type 2 innate lymphoid cells, eosinophils and dermis-resident macrophages, and ameliorates infection." (PMID 38030609, 2023). "We confirmed these observations and found that TSLP can activate Tfh cells and can stimulate the germinal center B cell response after infection with a live-attenuated virus by promoting the migration of dendritic cells from the mucosal tissue to the draining lymph nodes." (PMID 34659250, 2021). "In addition, compared to RV-A1B, RV-C15 infection induced significantly higher protein expression of IL-25, IL-33 and TSLP." (PMID 33968043, 2021). "HRV-16 (MOI = 1) infection induced both TSLP and CCL26 mRNA and protein expression in NHBE cells." (PMID 32120846, 2020). "In addition, VEGFα was increased in mutantGFP and non‐mutantTom KCs after Adeno‐Cre infection, while its expression was down‐regulated after TSLP neutralization in both populations (Fig EV5G)." (PMID 31556482, 2019). "Additionally, it has been described that hRSV infection in NHBEs cells induced the expression of TSLP transcript at 12 h post-infection and TSLP secretion exhibited a peak at 24 h post-infection as compared to ultraviolet (UV)-hRSV inactivated." (PMID 30936869, 2019). "Our previous studies have shown that delivery of TSLP to mice induced type-2 related protective immune responses against S. mansoni challenge infection, which could have involved the recruitment and activation of eosinophils, basophils, and mast cells." (PMID 28346516, 2017). "First, we assessed the level of TSLP in serum of mice after infection with T. congolense." (PMID 28769924, 2017). "We observed that infection with T. congolense induced TSLP expression in C57BL/6 mice, suggesting that this cytokine might play a role in T. congolense infection." (PMID 28769924, 2017). "Collectively, our study shows that TSLP-TSLPR engagement is needed in the late stages of infection to create a Th2 environment and optimal M2 macrophage response that would ultimately regulate infection-induced inflammation and prolong survival of infected animals." (PMID 28769924, 2017). "Finally, infection of mice with recent clinical isolates of RSV with known human pathogenic potential demonstrated a similar induction of IL-13+ ILC2s at day 4 after infection that required TSLP." (PMID 27156176, 2016). "This was surprising given that the peak of TSLP in the lungs occurred 12 hours after infection." (PMID 27156176, 2016). "Both thymic stromal lymphopoietin (TSLP) and IL-33 levels were increased 12 hours after infection." (PMID 27156176, 2016). "However, Fontenot and colleagues described HIV-induced TSLP mRNA expression in human genital epithelial cells in early stages of the infection." (PMID 27769179, 2016).
infection (continued). "Importantly, there was a statistically significant decrease in the number of IL-13+ ILC2s in the groups receiving TSLP neutralizing antibody at either 6 or 36 hours after infection compared with RSV-infected mice treated with isotype control antibody." (PMID 27156176, 2016). "In addition to these findings, increased production of IL-33 early during infection in resistant strains of mice has been correlated with increased production of the Th2-inducing cytokine TSLP." (PMID 23053395, 2012). "Moreover, epithelial cells from resistant animals have higher expression of chemokines such as CCL2, CCL3, CCL5, CCL20 and TSLP early during infection which correlates with the rapid mobilization of DCs to the large intestine." (PMID 23053395, 2012). "In addition, L. paracasei induced TSLP expression that peaked at 48 h from infection, while both L. plantarum and LGG induced a very transient production of TSLP." (PMID 19756155, 2009). "Neutralizing TSLP with antibodies or genetically removing TSLP specifically in dermal TRMs leads to a decrease in both the number of ILC2s and their interactions with dermal TRMs in infected skin, ultimately reducing the number of dermal TRMs and promoting greater control of the infection." (PMID 39349826, 2024). "However, heterologous infection with 2 RV serotypes induced TSLP protein." (PMID 38061015, 2024). "Recently, however, two studies have reported RV-C15 – a prevalent strain in humans that may cause severe symptoms – infection of C57BL/6J mice induced the upregulation of remodeling-associated genes MUC5AC and MUC5B, elevated IL-25, IL-33, and TSLP levels, and increased numbers of lung ILC2s." (PMID 37773065, 2023). "Despite the importance of TSLP regarding infection, the role of macrophage-derived TSLP is unknown." (PMID 31480519, 2019). "Interestingly, neutralization of TSLP significantly attenuated IL-13+ ILC2 induction during RSV infection irrespective of whether intervention occurred 6 or 36 hours after infection." (PMID 27156176, 2016). "After 9 days post-infection, the number of tracked tdTomato+ ILC2 in the field of view was about three-fold fewer in the TSLP-neutralized animal compared with immunoglobulin G (IgG) treated control (25 vs 90 tracked tdTomato+ ILC2s)." (PMID 38030609, 2023). "Our previous studies have indicated that primary cultures of alveolar epithelial cells type II from naïve mice had increased expression of epithelial cell-derived cytokines IL-33, TSLP and CCL2 after in vitro infection with RSV." (PMID 33923693, 2021). "The expression of IL-1β, IL-6, IL-8, IL-18, TNF-α, MMP-9, RANKL, TLR-2, TLR-4, TLR-6, thymic stromal lymphopoietin (TSLP), and ICAM-1 was evaluated by qPCR at 2 and 24 h after infection." (PMID 33802988, 2021). "Consequently, during the very first contact with HIV-1 at the genital mucosa—also the vaccine effector site—these imprinted immune cells could receive from HIV-1 envelope a signal to induce TSLP, and in turn rapidly mobilize vaccine induced memory cells to prevent infection." (PMID 33613520, 2020). "In this article, we will review recent studies of the role of IL-7 and TSLP in ILC development and function during infection and inflammation." (PMID 31921158, 2019). "Tuft cells produce IL-25 and thymic stromal lymphopoietin (TSLP) in response to helminths to induce Th2-type immune responses and protect against infection by a helminth." (PMID 31555282, 2019). "When neonatal mice are treated with antibodies to neutralize TSLP, IL-33 or their target expressed on DCs, OX40L, the ability of early RSV infection to prime pathological Th2 responses upon re-infection of adults is reduced." (PMID 29915592, 2018). "Drug cure resulted in a sudden decrease of most of the cytokines that became overexpressed after primary infection (IL-6, IL-9, IL-12, IL-33, IFN-γ and TSLP)." (PMID 27658962, 2016).